FBLL1 (fibrillarin like rRNA 2'-O-methyltransferase 1)
Description:
S-adenosyl-L-methionine-dependent RNA methyltransferase that catalyzes 2'-hydroxyl ribose methylation in RNAs. Functions as part of box C/D small nucleolar ribonucleoprotein (snoRNP) complexes, where guide snoRNAs ensure methylation specificity through base pairing with RNA substrates. Exhibits broad substrate specificity, methylating multiple sites on ribosomal RNAs (rRNAs) and messenger RNAs (mRNAs) depending on the guide snoRNA incorporated in the complex. Specifically expressed in brain, it regulates the expression of GAP43 by stabilizing its mRNA through methylation and thereby plays an indirect role in neuronal differentiation (By similarity).
Synonyms: LOC345630
Tractability: PROTAC: its protein half-life has been measured.
Gene: Protein-coding gene on chromosome 5 (168,529,305 to 168,530,634, forward strand). Ensembl gene ENSG00000188573.
Subcellular location: Nucleus, nucleolus
Subcellular location (Human Protein Atlas): Nucleoli fibrillar center; Nucleoplasm
Gene Ontology:
Molecular function: RNA 2'-O-methyltransferase activity; histone H2AQ104 methyltransferase activity; rRNA methyltransferase activity; methyltransferase activity; RNA binding
Biological process: box C/D sno(s)RNA 3'-end processing; mRNA modification; mRNA stabilization; neuron differentiation; rRNA 2'-O-methylation; rRNA methylation; chromatin remodeling; rRNA processing
Cellular component: box C/D methylation guide snoRNP complex; fibrillar center; nucleolus; Cajal body; small-subunit processome; ribonucleoprotein complex
Homologues: Orthologues: macaque FBLL1 (99% identical), pig FBLL1 (94% identical), chimpanzee FBLL1 (93% identical), rat Fbll1 (85% identical), mouse Fbll1 (84% identical), guinea pig FBLL1 (80% identical), dog FBLL1 (78% identical), zebrafish fbl (72% identical), Drosophila melanogaster Fib (70% identical), tropical clawed frog fbl (70% identical), Caenorhabditis elegans fib-1 (65% identical), Drosophila melanogaster CG10909 (36% identical). Paralogues in human: FBL (73% identical).
Diseases named in the same sentence as FBLL1 in open-access papers:
FBLL1 is named in the same sentence as 7 diseases in open-access papers, as found by Europe PMC text mining. Sharing a sentence is not in itself a finding about the gene and the disease. The quoted sentences say what the papers report.
liver cancer (3 papers, 2020 to 2026). An epithelial or non-epithelial malignant neoplasm that arises from the liver. "We analyzed the expression of SMG5, EZH2, FBLL1, ZNF239, and IGF2BP3 in liver cancer using the Oncomine database." (PMID 33297932, 2020).
tumor (1 paper, 2026). "Spatial and single-cell analyses showed that FBLL1 expression was preferentially enriched in malignant hepatocytes within the tumor region." (PMID 41677613, 2026).
FBLL1 also shares sentences with these, for which no sentence is quoted: cancer (3 papers); breast carcinoma (1); hepatocellular carcinoma (1); lung carcinoma (1); prostate carcinoma (1).